HBB (hemoglobin subunit beta)
Diseases named in the same sentence as HBB in open-access papers (continued):
Sharing a sentence is not in itself a finding about the gene and the disease.
thalassemia (continued). "Techniques such as Gap-PCR and PCR-RDB can only detect common types of thalassemia, which include four deletion α-thalassemias, three non-deletion α-thalassemias and 17 HBB gene mutations." (PMID 36159974, 2022). "Compared to conventional methods, SMRT technology detected more abnormal hemoglobin variant sites on the HBA1, HBA2, and HBB genes, which illustrated the value of SMRT technology in the diagnosis of common and rare types of α-thalassemia and β-thalassemia variants." (PMID 34690349, 2022). "All those samples were detected common mutations in the HBB gene and common nondeletional/deletional α thalassemia." (PMID 34492731, 2021). "Here, we describe a novel approach to simultaneously detect a set of 18 HBB mutations, as well as 2 HFE mutations in chronically transfused pediatric and adolescent thalassemia patients, including the determination of the abundance of these mutations in several ethnic groups in Pakistan." (PMID 32414341, 2020). "In ß-thalassemia patient-derived iPSCs, piggyBac transposon-mediated puro∆tk-based drug selection was used in combination with CRISPR/Cas9 to achieve correction of the mutation in the Hemoglobin Beta Chain (HBB) gene." (PMID 30899334, 2019). "Thalassemia is a common monogenic disease including two major types, α‐ and β‐thalassemia, according to mutations or deletions in α‐ and β‐globin genes (HBA1, HBA2 and HBB; OMIM: 141800, 141850 and 141900), respectively." (PMID 30968607, 2019). "Two large‐deletion variants of HBB (Patient #5 and #11) were detected and verified by specific PCR, whereas common screening of thalassemia genes and Sanger sequencing could not identify them." (PMID 41532136, 2026). "For traditional thalassemia genetic diagnosis, the reverse dot blot hybridization, Sanger sequencing, GAP-PCR and Multiple ligation-dependent probe amplification (MLPA) can be utilized to detect the prevalent variants, including SNVs, indels and copy number variations in HBB and HBA1/212." (PMID 35701592, 2022). "In southern China, the most prevalent variants of α-thalassemia are -α3.7 deletion, --SEA deletion, -α4.2 deletion, HBA2 c.369C>G, and HBA2 c.427T>C, while those of β-thalassemia are HBB c.126_129delCTTT, HBB c.52A>T, HBB c.316-197C>T, HBB c.-78A>G, and HBB c.79G>A." (PMID 33546747, 2021). "Moreover, compound heterozygosity for the mutation results in severe thalassemia phenotypes, comparable to the combination with mutations characterized by a complete absence of HBB expression (β0 mutations)." (PMID 32933098, 2020). "By analyzing previously published thalassemia data from the Dai people in Dehong and Xishuangbanna (two regions in Yunnan Province, China), we found that several sequence types, including HBA CNV and HBB mutations, significantly depend on gender in Xishuangbanna but not in Dehong." (PMID 30940865, 2019). "Beyond that, we identified six rare thalassemia genotypes: HBA2 c.272_279delAGCTTCGG heterozygote, HBB c.180G>C heterozygote, HBB c.341T>A heterozygote, HBB c.68A>C heterozygote, HBB c.68A>G heterozygote, and heterozygous deletion of HBB exons 1-3." (PMID 38660679, 2024). "In our study, 30% of HBB LoF heterozygotes with a thalassemia diagnosis and 16% of heterozygotes without a thalassemia diagnosis had a diagnosis of iron deficiency anemia, driving a statistically significant association with this trait (compared to only 6% of those without a HBB LoF variant)." (PMID 34385667, 2021). "Subjects HFY07, HFY21, and HFY47 had no thalassemia variants but other SNVs detected in their HBB genes by CATSA; HFY07 and HFY21 harbored HBB:c.315+308delA heterozygote; and HFY47 harbored HBB:c.315+337A>G heterozygote." (PMID 36685902, 2022). "Trio-WES found no mutations for thalassemia-related genes such as HBA1 and HBA2 for α-thalassemia and HBB for β-thalassemia." (PMID 36385762, 2022). "ß-thalassemia is characterized by reduced or absent expression of HBB." (PMID 30645582, 2019).
thalassemia (continued). "The tests however may not easily differentiate Sβ0 thalassemia from SS, and in this case HBB gene sequencing is necessary." (PMID 31830127, 2019). "Some of these predictions might be redundant, such as for the disease ALPHA-THALASSEMIA (OMIM: 604131), the gene HBB, which is short for HEMOGLOBIN--BETA LOCUS, is obviously a cause of another type of thalassemia called BETA-THALASSEMIA (OMIM: 613985) but not ALPHA-THALASSEMIA." (PMID 26818594, 2016).
beta thalassemia (66 papers, 2005 to 2025). Beta-thalassemia (BT) is characterized by deficiency (Beta+) or absence (Beta0) of synthesis of the beta globin chains of hemoglobin (Hb). "Homozygous or compound heterozygous mutations in the beta globin (HBB) gene (*141900) cause beta thalassemia." (PMID 41413825, 2025). "The other HBB variant (NM_000518.4:c.315+1 G > A) has been previously reported in patients with autosomal recessive beta-thalassemia (HGMD database) and ClinVar (Variation ID: 15438 – P)." (PMID 39870877, 2025). "Beta-thalassemia exhibits a broad phenotypic range influenced by the severity of HBB mutation and various genetic modifiers." (PMID 40129579, 2025). "Beta-thalassemia is one of the most prevalent inherited hematological diseases with about 350 mutations in the β-globin gene (HBB) located on chromosome 11." (PMID 38919232, 2024). "Beta-thalassemia is one of the most common inherited hematological diseases caused by more than 350 mutations in the β-globin gene (HBB)." (PMID 38919232, 2024). "Beta thalassemia can be caused by a variety of molecular variants, ranging from point mutations to small deletions limited to the adult beta globin gene (HBB) (OMIM *141900) to large deletions involving the whole beta globin gene cluster." (PMID 38535125, 2024). "Beta thalassemia, a genetic disorder caused by the coding of the beta-globin gene of hemoglobin (HBB), is characterized by hemolytic anemia and ineffective erythropoiesis." (PMID 39735486, 2024). "This study aims to examine and identify mutations in the exon 1 region of the HBB gene in beta-thalassemia patients from the Vijayapura region." (PMID 39176330, 2024). "Electroporation has been used to deliver CRISPR/Cas9 components to edit the HBB gene that causes beta thalassemia in hematopoietic stem cells, as well as to correct a genetic mutation that causes cystic fibrosis in airway epithelial cells." (PMID 37222810, 2023). "Beta-thalassemia (beta-thal) is a common genetic disease caused by one or several nucleotide substitutions, insertions, or deletions within the HBB (beta-globin) gene." (PMID 35563395, 2022). "Beta thalassaemia is caused by mutations which reduce or eliminate beta globin production from the beta globin locus (HBB)." (PMID 35624125, 2022). "The HBB variant is recorded in ClinVar as pathogenic for beta-thalassemia, and the gene is annotated in Orphanet for this disease." (PMID 35945607, 2022). "The sequences of these molecules reflect clinically relevant targets previously used to correct a pathologic beta-thalassemia-associated splicing mutation in the human HBB (hemoglobin subunit beta) gene in transgenic mice." (PMID 35988651, 2022). "Using PE3, we successfully installed the beta-thalassemia (beta-thal) mutations in the HBB gene in the erythroid progenitor cell line HUDEP-2." (PMID 35563395, 2022). "From the analysis of single-based association, two intronic polymorphisms; IVS2-16G>C, and IVS2-666C>T, and one variant at 3' untranslated region to HBB gene assigned as 3'UTR + 314G>A were found significantly associated with beta-thalassemia." (PMID 34408192, 2021). "This study has identified the potential use of intragenic polymorphic markers in the HBB gene, which were significantly associated with beta-thalassemia." (PMID 34408192, 2021). "Beta-thalassemia (β-thalassemia) is one of the most common genetic diseases and is mainly caused by point mutations or small deletions in the beta-globin gene (HBB)." (PMID 35126312, 2021). "Variant interpretation is demonstrated on a 5’UTR variant of the gene HBB associated with beta-thalassemia." (PMID 33970899, 2021). "Beta-thalassemia is due to decreased beta-globin chain synthesis of which, caused by a mutation in the HBB gene." (PMID 34408192, 2021). "We have also demonstrated that the pathogenic mutation of beta-thalassemia was c.52A > T (p.Lys18Ter) of HBB (NM_000518.5) which is very common in the Chinese population." (PMID 32351539, 2020).
beta thalassemia (continued). "We demonstrated the clinical utility of molecular phenotyping in clinical hemoglobinopathies by mapping out the spectrum of heterozygous HbE, HbD and a heterozygous beta thalassemia (HBB:c.27_28insG) variants." (PMID 32985608, 2020). "The most frequent beta thalassemia mutations of Sβ0 and Sβ+ were HBB: c.118C>T (Gln40Stop) and HBB c.92 + 6T> C, respectively." (PMID 31830127, 2019). "Mutations in the HBB gene other than in the positions c.79 and c.92 + 5 usually occur as co-existing partners either with c.79G > A or c.92 + 5G > C in beta-thalassemia patients." (PMID 29295702, 2018). "Beta-thalassemia is caused by mutations in the adult beta-globin gene (HBB) and is one of the most prevalent monogenic blood disorders worldwide." (PMID 31069325, 2018). "Inherited mutations or deletions at the HBB gene locus on chromosome 11p15.4 cause beta-thalassemia." (PMID 23861885, 2013). "Over 600 mutations have been described in the HBB gene, of which more than 200 are associated with a beta-thalassemia phenotype." (PMID 18694524, 2008). "Mutations in the HBB gene cause beta-thalassemia (β-thalassemia)." (PMID 40129579, 2025). "Beta-thalassemia carrier or trait is associated with defects in one allele of the HBB gene." (PMID 38919232, 2024). "Besides rare deletion and rare mutation in the HBB gene, duplication of α-globin genes coexisted with β thalassemia was also a common cause for prenatal diagnosis to avoid children with rare beta thalassemia-major (6/42, 14.28%)." (PMID 37529778, 2023). "In addition to the sickle trait gene (HBB), our mapping strategies identified other members of beta globin gene cluster that cause various forms of beta-thalassemia (HBE1, HBD, HBG, and HBG2)." (PMID 34868193, 2021). "To offer an illustration of how variants effects are predicted in a specific sequence, we provide the results of a model interpretation procedure for the 5’UTR sequence of the HBB gene (HBB-001), which plays a role in beta-thalassemia and has known 5’UTR variants." (PMID 33970899, 2021). "The association data on a single genotype and haplotype might disclose the effect of HBB polymorphisms in beta-thalassemia that might provide an impact in the understanding of beta-thalassemia propensity." (PMID 34408192, 2021). "In this study, five single nucleotide polymorphisms (SNPs) within the HBB gene were evaluated to determine its significance and haplotype structure inference with beta-thalassemia in Malaysia, which was the first study conducted in Malaysia to the best of our knowledge." (PMID 34408192, 2021). "Therefore, the identification of nucleic acid variations in the HBB gene has improved our understanding of underlying causal mutations of beta-thalassemia in Malaysia." (PMID 34408192, 2021). "There are several reasons for the reduction of HBB expression; for example, partial deletion of the terminal portion of HBB gene, nonsense mutation and frameshift deletion cause beta-thalassemia." (PMID 15956966, 2005). "That SUPT5H acts as modifier in beta-thalassemia carriers became evident from three reported cases in whom combined heterozygosity of SUPT5H and HBB gene variants was observed to resemble a mild beta-thalassemia intermedia phenotype." (PMID 39201615, 2024). "The earliest pathogenic intronic AG-gain variants, as we found, was published in 1981, with the report of an intronic base substitution in gene HBB from a Greek girl with beta-thalassemia." (PMID 37931111, 2023). "Missense p.Glu27Lys, nonsense p.Lys18Ter variants, and splicing errors such as c.92 + 1G > T and c.315 + 1G > A within HBB were identified in four beta thalassemia cases." (PMID 36832257, 2023). "Here we report on the combined testing of a single gene defect (beta thalassemia-HBB) and preimplantation genetic testing for aneuploidy (PGT-A) in a single tube with a single sequencing run." (PMID 33216308, 2021).
beta thalassemia (continued). "This haplotype-based association analysis was carried out to provide a prediction of the predisposing effect and reveal the severity and possible prognosis using haplotype-tagged SNPs of HBB gene for beta-thalassemia." (PMID 34408192, 2021). "A variant in the 3'UTR of the HBB gene, which is assigned as 3'UTR + 314 G>A was found to have a significant susceptibility effect towards beta-thalassemia with the odds ratio 2.013 (p = 0.004)." (PMID 34408192, 2021). "Similar to India, only five mutations, including c.-78A > G, c.52A > T, c.126_129delCTTT, c.216_217insA and c.316-197C > T in HBB gene are responsible for 90% of beta-thalassemia patients in china." (PMID 29295702, 2018). "Screening all exons in the HBB gene has proven beneficial in preventing beta-thalassemia." (PMID 39176330, 2024). "The elevated levels of HbA2 in the absence of a beta-thalassemia trait causing variants in the HBB gene is one of the most suggestive elements to identify variants in the SUPT5H gene." (PMID 39201615, 2024). "Additional LoF variants in SUPT5H were found in several other individuals of Dutch, French and Italian ancestry, all of whom presented hematological characteristics consistent with beta-thalassemia traits but were negative for variants in the HBB genes." (PMID 39201615, 2024). "Several members of two unrelated Dutch families showing beta-thalassemia trait with a characteristic of elevated HbA2 and microcytic hypochromic anemia were analyzed by Sanger sequencing, which revealed two completely normal copies of the HBB gene." (PMID 34385932, 2021). "In addition, the analysis also reveals that both Royal Kelantan Malay genomes shared 3 SNP markers; HBG1 (rs1061234), HBB (rs1609812) and BCL11A (rs766432) where all three markers were associated with beta-thalassemia." (PMID 27090252, 2014). "Five genes mapped to hemoglobin subunits (HBG1, HBG2, HBE1, HBB and HBD) involved in beta thalassemia and fetal hemoglobin quantitative trait locus 1 diseases." (PMID 38627641, 2024). "A total of eight different pathogenic variants in the SUPT5H gene have been identified in 25 patients with a similar beta-thalassemia minor phenotype showing no abnormalities in the HBB gene (16, Dutch; 2, French; and 7, Greek)." (PMID 34385932, 2021). "In very rare cases, haplotype analysis may reveal a pattern of inheritance that does not segregate with the locus of the HBB gene located within the so-called beta-globin gene cluster (chromosome 11 p15), so-called unlinked beta-thalassemia." (PMID 39201615, 2024).
malaria (42 papers, 2011 to 2025). Malaria is a serious and sometimes fatal disease caused by a parasite that commonly infects a certain type of mosquito which feeds on humans. "The protective association between variants in HBB and severe Plasmodium falciparum malaria results in a higher prevalence of HBB mutations in geographic areas with high malaria prevalences." (PMID 38547025, 2024). "The prominent signal occurs 24 kb upstream of HBB, a well-known gene associated with malaria resistance." (PMID 39288167, 2024). "The strongest genome-wide association with severe malaria mapped to a region close to the hemoglobin HBB gene on chromosome 11p15, where the HbS polymorphism is located." (PMID 35646724, 2022). "Multiple prior studies have established that the Hemoglobin Subunit Beta (HBB) gene to be a significant genetic risk factor for malaria because of its risk alleles." (PMID 35934714, 2022). "GWAS has identified numerous SNPs associated with severe Plasmodium infections, however, only a few variant genes and their polymorphisms, such as ATP2B4 and HBB, have been experimentally confirmed to be involved with malaria pathogenesis." (PMID 35646724, 2022). "Several other genes with genetic variants associated with resistance to malaria (e.g. HBB, ABO) are under balancing selection." (PMID 34449765, 2021). "Polymorphisms in the HBB gene, haemoglobin S (HbS, sickle cell trait) and haemoglobin C (HbC) protect against severe malaria." (PMID 30665411, 2019). "These markers were complemented by 180 SNPs within malaria candidate genes, including HBB (encoding HbS) on the same cases and controls." (PMID 29381699, 2018). "For example, the rs334 mutation in HBB contributes only 2·9% to the total variance in risk for severe malaria despite its large effect size because protection is only afforded to a small proportion (about 15%) of the population." (PMID 30033078, 2018). "Variation in the HBB gene has also been found to be associated with malaria protection by GWAS, and interestingly, has been associated with a significant host to vector P. falciparum transmission." (PMID 30405986, 2018). "HBB, a gene known to harbor alleles conferring protection against malaria and to be a target of balancing selection, is among the genes showing strong differentiation in our dataset." (PMID 26553317, 2015). "These include SNPs near established malaria susceptibility loci; in the beta globin (HBB) gene on chromosome 11 and in the ABO blood group gene (ABO) on chromosome 9." (PMID 23717212, 2013). "Three loci previously associated with resistance to malaria—HBB (11p15.4), HBA1/HBA2 (16p13.3), and G6PD (Xq28)—were associated (P ≤ 1 × 10−6) with RBC traits in the discovery cohort." (PMID 23696099, 2013). "In contrast, HbC that was negatively associated with maximum parasitemia and mild malaria was positively associated with anti-malarial IgG levels in the same population, further suggesting that HBB polymorphisms alter the anti-malarial IgG production." (PMID 22947458, 2012). "Polymorphisms in the HBB gene may also increase the likelihood that malaria-infected individuals infect mosquitoes." (PMID 30665411, 2019). "Recent efforts at elaborating a genetic architecture of malaria have focused on severe malaria, leading to the identification of two new genes and confirmation of previously known variants in HBB, ABO and G6PD, by exploring the whole human genome in genome-wide association (GWA) studies." (PMID 25887595, 2015). "Haemoglobin S (HbS) and C (HbC) are variants of the HBB gene which both protect against malaria." (PMID 22506028, 2012). "Haldane's hypothesis was confirmed by A. C. Allison, who showed that the geographical distribution of the sickle‐cell mutation in the beta hemoglobin gene (HBB) was limited to Africa and correlated with malaria endemicity, and individuals who carried the sickle‐cell trait were resistant to malaria." (PMID 37216026, 2023).